ZDHHC3 (zDHHC palmitoyltransferase 3)
Description:
Golgi-localized palmitoyltransferase that catalyzes the addition of palmitate onto various protein substrates. Has no stringent fatty acid selectivity and in addition to palmitate can also transfer onto target proteins myristate from tetradecanoyl-CoA and stearate from octadecanoyl-CoA (By similarity). Plays an important role in G protein-coupled receptor signaling pathways involving GNAQ and potentially other heterotrimeric G proteins by regulating their dynamic association with the plasma membrane. Palmitoylates ITGA6 and ITGB4, thereby regulating the alpha-6/beta-4 integrin localization, expression and function in cell adhesion to laminin. Plays a role in the TRAIL-activated apoptotic signaling pathway most probably through the palmitoylation and localization to the plasma membrane of TNFRSF10A. In the brain, by palmitoylating the gamma subunit GABRG2 of GABA(A) receptors and regulating their postsynaptic accumulation, plays a role in synaptic GABAergic inhibitory function and GABAergic innervation (By similarity). Palmitoylates the neuronal protein GAP43 which is also involved in the formation of GABAergic synapses (By similarity). Palmitoylates NCDN thereby regulating its association with endosome membranes (By similarity). Probably palmitoylates PRCD and is involved in its proper localization within the photoreceptor (By similarity). Could mediate the palmitoylation of NCAM1 and regulate neurite outgrowth (By similarity). Could palmitoylate DNAJC5 and regulate its localization to Golgi membranes (By similarity). Also constitutively palmitoylates DLG4 (By similarity). May also palmitoylate SNAP25 (By similarity). Could palmitoylate the glutamate receptors GRIA1 and GRIA2 but this has not been confirmed in vivo (By similarity). Could also palmitoylate the D(2) dopamine receptor DRD2. May also palmitoylate LAMTOR1, promoting its localization to lysosomal membranes. Palmitoylates the Toll-like receptor 9/TLR9 in the Golgi and thereby regulates TLR9 trafficking to endosomes. May palmitoylate CALHM1 and CALHM3 subunits of gustatory voltage-gated ion channels and modulate channel gating and kinetics (By similarity). Catalyzes the palmitoylation of CADM4 at 'Cys-347', ensuring its localization to the plasma membrane (PM) and protein stability (By similarity). The presence of CADM4 at the PM is essential for its function in CNS myelination, particularly through its associations with other cell adhesion molecules (By similarity). May also function as a calcium transporter.
Synonyms: DHHC-3; ZNF373; GODZ; DHHC3
Tractability: Antibody: UniProt predicts a signal peptide or a membrane-spanning region. PROTAC: ubiquitination databases record sites on it; its protein half-life has been measured.
Target class: Enzyme; Transferase
Gene: Protein-coding gene on chromosome 3 (44,915,257 to 44,976,185, reverse strand). Ensembl gene ENSG00000163812.
Subcellular location: Golgi apparatus membrane
Subcellular location (Human Protein Atlas): Golgi apparatus
Pathways (Reactome):
Disease: Maturation of spike protein
Gene Ontology:
Molecular function: palmitoyltransferase activity; protein-cysteine S-palmitoyltransferase activity; protein homodimerization activity; protein-cysteine S-myristoyltransferase activity; protein-cysteine S-stearoyltransferase activity
Biological process: lipoprotein localization to membrane; positive regulation of toll-like receptor 9 signaling pathway; protein localization to photoreceptor outer segment; protein localization to plasma membrane; protein palmitoylation; regulation of G protein-coupled receptor signaling pathway; TRAIL-activated apoptotic signaling pathway; peptidyl-L-cysteine S-palmitoylation; positive regulation of receptor localization to synapse; positive regulation of synaptic transmission, GABAergic; protein localization to membrane; protein targeting to membrane
Cellular component: Golgi apparatus; Golgi membrane; membrane; endoplasmic reticulum
Genetic constraint (gnomAD): Loss-of-function variants: 11 observed, 36.55 expected, observed/expected ratio (o/e) 0.3, 90% interval 0.19 to 0.5. The upper end of that interval is the gene's LOEUF score, 0.5, which puts it in group 2 of 6, group 1 being the genes least tolerant of losing a copy. Missense variants: 246 observed, 404.52 expected, observed/expected ratio (o/e) 0.61, 90% interval 0.55 to 0.68. Synonymous variants: 136 observed, 148.3 expected, observed/expected ratio (o/e) 0.92, 90% interval 0.8 to 1.06.
Homologues: Orthologues: chimpanzee ZDHHC3 (100% identical), mouse Zdhhc3 (97% identical), guinea pig ZDHHC3 (97% identical), rat Zdhhc3 (87% identical), dog ZDHHC3 (86% identical), pig ZDHHC3 (86% identical), tropical clawed frog zdhhc3 (77% identical), zebrafish zdhhc3a (73% identical), macaque ZDHHC3 (61% identical), Drosophila melanogaster CG8314 (56% identical), Caenorhabditis elegans dhhc-3 (47% identical). Paralogues in human: ZDHHC7 (62% identical), ZDHHC21 (28% identical), ZDHHC1 (27% identical), ZDHHC6 (27% identical), ZDHHC20 (25% identical), ZDHHC2 (24% identical), ZDHHC15 (23% identical), ZDHHC9 (23% identical), ZDHHC14 (23% identical), ZDHHC12 (22% identical), ZDHHC18 (21% identical), ZDHHC19 (21% identical), and 5 more.
Diseases named in the same sentence as ZDHHC3 in open-access papers:
ZDHHC3 is named in the same sentence as 43 diseases in open-access papers, as found by Europe PMC text mining. Sharing a sentence is not in itself a finding about the gene and the disease. The quoted sentences say what the papers report.
breast cancer (12 papers, 2019 to 2025). A primary or metastatic malignant neoplasm involving the breast. "In breast cancer, patients associated with an elevated expression of ZDHHC3 were correlated with lower patient survival." (PMID 37759431, 2023). "ZDHHC3 is overexpressed in breast cancer and high ZDHHC3 expression results in unfavorable survival of patients with breast cancer." (PMID 38177255, 2024). "Intriguingly, curcumin, a natural polyphenol component of Curcuma longa, effectively inhibited breast cancer cell invasion by blocking autopalmitoylation of ZDHHC3, which regulates ITGβ4 palmitoylation." (PMID 36018061, 2023). "On the contrary, the palmitoylation of integrin β4 (ITGβ4) at cysteines Cys732, Cys736, Cys738, Cys739, and Cys742 by ZDHHC3 maintains its level in lipid rafts and promotes the invasive ability of breast cancer cells." (PMID 36018061, 2023). "Our prognostic signature consists of seven genes: Previous studies on cervical and breast cancer found that ZDHHC3, Zinc Finger DHHC-Type Palmitoyltransferase 3, was highly expressed in cervical cancer and showed copy number amplification after HPV infection." (PMID 37168510, 2023). "Two palmitoyltransferases, ZDHHC9 in breast cancer and ZDHHC3 (DHHC3) in colorectal cancer, attach palmitate to the C272 site of PD-L1." (PMID 34829931, 2021). "Here, the authors identify that in breast cancer cells ZDHHC3-catalyzed B7-H4 palmitoylation prevents its lysosomal degradation and maintains immune suppression, which can be targeted by Abemaciclib to enhance lysosome activation independently of CDK4/6 inhibition." (PMID 40341398, 2025). "The ZDHHC3 protein is expressed in all breast cancer (BRCA) and HNSCpatients, and in almost all pan-cancer, cervical cancer (CES), and skin cancer and melanoma (SKCM) patients based on immunohistochemistry staining examination results in the Human Protein Atlas database." (PMID 39349454, 2024). "ZDHHC3 inhibits breast cancer cell growth while also promoting oxidative stress and aging." (PMID 37168510, 2023). "We find that ZDHHC3, a zinc finger DHHC-type palmitoyltransferase, palmitoylates B7-H4 at Cys130 in breast cancer cells, preventing its lysosomal degradation and sustaining B7-H4-mediated immunosuppression." (PMID 40341398, 2025). "Taken together, these findings proved in principal that ZDHHC3 and APT1 are potential pharmaceutical targets for treating breast cancer." (PMID 36018061, 2023). "The pathological significance of the interplay between B7-H4 and ZDHHC3 in non-tumor cells in the breast cancer microenvironment remains to be studied." (PMID 40341398, 2025). "Of note, unlike ZDHHC9-mediated PD-L1 palmitoylation in breast cancer cells, palmitoylation of PD-L1 in colorectal cancer cells is mediated by ZDHHC3 but not ZDHHC9, indicating that PD-L1 utilizes multiple ZDHHCs to ensure its palmitoylation in different contexts." (PMID 37759431, 2023). "Although both ZDHHC3 and APT1 depletion seem to have a similar effect on preventing the proliferation of the same breast cancer cell (MDA‐MB‐231), the molecular mechanisms might be different, as ZDHHC3 regulates oxidative stress and senescence, while APT1 is involved in controlling apoptosis." (PMID 36018061, 2023).
cervical cancer (5 papers, 2023 to 2024). A primary or metastatic malignant neoplasm involving the cervix. "We synthesized a stapled peptide-based PROTAC (SP-PROTAC) that specifically targeted palmitoyltransferase ZDHHC3 and resulted in the decrease of PD-L1 in human cervical cancer cell lines." (PMID 37325638, 2023).
colorectal cancer (3 papers, 2021 to 2024). A primary or metastatic malignant neoplasm that affects the colon or rectum. "Recent studies have highlighted the role of ZDHHC3-mediated palmitoylation of PD-L1 in colorectal cancer, which blocks PD-L1 degradation by lysosomes and suppresses antitumor immunity." (PMID 37875591, 2023).
dilated cardiomyopathy (3 papers, 2023 to 2025). Cardiomyopathy which is characterized by dilation and contractile dysfunction of the left and right ventricles. "Conversely, Zdhhc3 overexpression causes severe dilated cardiomyopathy that is associated with an increase in palmitoylated Rac1 levels, suggesting that both enhancing or disrupting Rac1 palmitoylation at cysteine-178 can have detrimental effects on cardiac adaptation and remodeling." (PMID 41333012, 2025). "Cardiomyocyte-specific overexpression of the Golgi-localized palmitoylating S-acyltransferase enzyme, zDHHC3, resulted in severe dilated cardiomyopathy which coincided with increased palmitoylated and active Rac1 levels." (PMID 41333012, 2025). "Transgenic mice with cardiomyocyte-specific overexpression of the Golgi enzyme, zDHHC9, exhibit normal cardiac function in young adulthood but develop dilated cardiomyopathy with advanced age, albeit relatively mild compared with overexpression of zDHHC3." (PMID 38385554, 2024). "We found that Rac1 is a novel substrate of zDHHC3 using an unbiased proteomic approach and that cardiomyocyte-specific transgenic mice overexpressing Zdhhc3, but not an enzymatically dead mutant, develop lethal dilated cardiomyopathy." (PMID 37926281, 2023).
Insulin resistance (3 papers, 2017 to 2024). Increased resistance towards insulin, that is, diminished effectiveness of insulin in reducing blood glucose levels. "To demonstrate the causative role of zDHHC3/GluA1 pathway in the synaptic plasticity deficit induced by insulin resistance, we performed LTP experiments in hippocampal organotypic slices biolistically transfected with plasmid-encoding shRNA for zDHHC3." (PMID 29222408, 2017). "Moreover, hippocampus-selective silencing of zDHHC3 or overexpression of the palmitoylation-deficient GluA1 mutant rescue the synaptic plasticity deterioration induced by insulin resistance." (PMID 29222408, 2017). "Here, we demonstrate that HFD increases palmitic acid deposition in the hippocampus and induces hippocampal insulin resistance leading to FoxO3a-mediated overexpression of the palmitoyltransferase zDHHC3." (PMID 29222408, 2017). "Here, we demonstrate that HFD-induced brain insulin resistance causes LTP and memory impairment due to the accumulation of palmitic acid and increased expression/activation of zDHHC3 leading to hyper-palmitoylation of GluA1 in the hippocampus." (PMID 29222408, 2017). "To better characterize the insulin resistance-dependent upregulation of PAT, we investigated the hypothesis that FoxO3a transcriptionally regulated zDHHC3." (PMID 29222408, 2017).
cardiac hypertrophy (2 papers, 2023 to 2025). "Further investigation identified Rac1 as a target of zDHHC3 in the heart, and both Zdhhc3 and Zdhhc7 were shown to be important in the initiation of cardiac hypertrophy with pressure overload stimulation." (PMID 37926281, 2023). "Genetic deletion of Zdhhc3 in combination with Zdhhc7 reduces cardiac hypertrophy during the early response to pressure overload stimulation but not over longer time periods." (PMID 37926281, 2023). "Here we performed a gain-of-function screen in the mouse and identified the Golgi-localized enzymes zDHHC3 and zDHHC7 as regulators of cardiac hypertrophy." (PMID 37926281, 2023). "Cardiac overexpression of Zdhhc3 complementary DNA (cDNA) resulted in cardiac enlargement including ventricular and atrial dilation, cardiac hypertrophy, and substantial cardiac dysfunction indicative of cardiomyopathy." (PMID 37926281, 2023). "Notably, induction of Rac1 S-palmitoylation in DTgZdhhc3 hearts occurred within 2 weeks of transgene expression, prior to the development of cardiac hypertrophy and heart failure, suggesting that modification of Rac1 may be a proximal mechanism underlying zDHHC3 activity–induced cardiac pathology." (PMID 37926281, 2023). "However, genetic deletion of Rac1 in the heart is unable to rescue cardiac maladaptation observed with zDHHC3 overexpression, and Zdhhc3 heart-specific null mice still show robust cardiac hypertrophy over 8 weeks of TAC stimulation or 2 weeks of Ang-II infusion." (PMID 37926281, 2023). "The key role of gene-based regulatory mechanisms: “ZDHHC3 and ZDHHC7, localized in the Golgi apparatus, have been identified as key regulatory factors in cardiac hypertrophy because they participate in the palmitoylation process of RAC1." (PMID 40969373, 2025). "Moreover, cardiac hypertrophy in response to 2 weeks of chronic angiotensin-II infusion was not significantly altered by deletion of Zdhhc3 or Zdhhc7 alone or in combination." (PMID 37926281, 2023). "Indeed, cardiac hypertrophy in response to 2 weeks of angiotensin-II infusion is not diminished by Zdhhc3/7 deletion, again suggesting other S-acyltransferases or signaling mechanisms compensate to promote hypertrophic signaling." (PMID 37926281, 2023).
epilepsy (2 papers, 2021 to 2023). A brain disorder characterized by episodes of abnormally increased neuronal discharge resulting in transient episodes of sensory or motor neurological dysfunction, or psychic dysfunction. "For instance, pathological neuronal activity observed in the temporal neocortex of intractable epilepsy patients and in the hippocampus and cortex of rats with experimentally induced epilepsy was linked with neuron-specific downregulation of ZDHHC3 mRNA and protein." (PMID 36766729, 2023). "Therefore, it has been speculated that the decrease in ZDHHC3 may have a detrimental effect on the function of GABAergic synapses, promoting NMDARs and AMPARs localization on the neuronal surface, and in this way contribute to epilepsy." (PMID 36766729, 2023).
glioma (2 papers, 2020 to 2022). A benign or malignant brain and spinal cord tumor that arises from glial cells (astrocytes, oligodendrocytes, ependymal cells). "Mechanically, ALKBH5 deficiency impairs the YTHDF2-mediated stability of ZDHHC3 mRNA, thereby suppressing PD-L1 expression by accelerating PD-L1 degradation in glioma." (PMID 36566230, 2022). "IHC staining of the glioma surgical specimen also indicated that ZDHHC3 expression was higher in WHO III-IV glioma than in WHO II glioma and was higher in recurrent GBM than in primary GBM." (PMID 36566230, 2022). "Therefore, ZDHHC3 was selected as the candidate target of ALKBH5 in glioma for further investigation." (PMID 36566230, 2022). "Analysis of TCGA and CGGA databases suggested that elevated expression of ZDHHC3 positively correlated with glioma malignancy according to WHO grading and predicted poor prognosis of glioma patients." (PMID 36566230, 2022).
heart failure (2 papers, 2023 to 2024). Inability of the heart to pump blood at an adequate rate to meet tissue metabolic requirements. "Here, we performed an in vivo screen using recombinant adeno-associated virus (AAV)-mediated overexpression, which identified the closely related Golgi-localized enzymes zDHHC3 and zDHHC7 as inducers of cardiac maladaptation, decompensation, and heart failure." (PMID 37926281, 2023). "zDHHC3 overexpression also elicited robust enhancement of Rac1 activity and translocation to the sarcolemma, along with induction of the protein levels of all Rho family small GTPases, all of which preceded heart failure in zDHHC3 transgenic mice." (PMID 38385554, 2024). "Indeed, zDHHC3 transgenic mice develop cardiomyopathy and heart failure with enhanced Rac1 S-palmitoylation and plasma membrane localization, along with activation of other Rho GTPase family members." (PMID 37926281, 2023).
Nonalcoholic Steatohepatitis (2 papers, 2023 to 2024). "ZDHHC3 exacerbates the development of nonalcoholic steatohepatitis (NASH) and the progression of hepatocellular carcinoma (HCC) associated to NASH by boosting the accumulation of lipids regulated by IRHOM2 and the production of lipids mediated by FASN signaling." (PMID 39148124, 2024).
pancreatic cancer (2 papers, 2024). "Previous studies have shown that inhibition of some members of the zDHHC family such as zDHHC3, 5, 17, 9, 12 inhibited tumor progression and enhanced the therapeutic efficacy of PD-1/PD-L1 checkpoint antibody blockade in CRC, glioblastoma, leukemia, and pancreatic cancer." (PMID 38415253, 2024).
Anxiety (1 paper, 2024). Intense feelings of nervousness, tension, or panic often arise in response to interpersonal stresses. "The results demonstrated that both Cadm4-KI and ZDHHC3-KO mice exhibited impairments in learning and memory, as well as altered behavior in anxiety-like tasks when compared to WT mice." (PMID 39327467, 2024).
bone cancer (1 paper, 2023). A primary or metastatic malignant neoplasm affecting the bone or articular cartilage. "Some patterns of expression were consistent across the two datasets, including high expression of ZDHHC3 and ABHD6 in bone cancer derived cell lines, particularly those derived from Ewing’s sarcoma tumors." (PMID 36760531, 2023).
cardiomyopathy (1 paper, 2023). A disease of the heart muscle or myocardium proper. "Here, we surveyed zDHHC S-acyltransferase enzymes and observed that activity of zDHHC3 and zDHHC7 at the cytoplasmic surface of the Golgi promotes hypertrophic signaling and cardiomyopathy in vivo." (PMID 37926281, 2023). "More importantly, deletion of Lgals1 did not impact cardiomyopathy and the reduction in fractional shortening caused by Zdhhc3 overexpression." (PMID 37926281, 2023). "However, loss of Rac1 or other identified zDHHC3 targets Gαq/11 or galectin-1 does not diminish zDHHC3-induced cardiomyopathy, suggesting multiple effectors and pathways promoting decompensation with sustained zDHHC3 activity." (PMID 37926281, 2023). "The most homologous S-acyltransferase to zDHHC3 is another Golgi-localized enzyme, zDHHC7, and AAV9-mediated overexpression of this enzyme in the heart similarly induced cardiomyopathy within 3 weeks." (PMID 37926281, 2023). "Overexpression of Zdhhc3 for the first time in the adult heart did not result in immediate cardiomyopathy as observed with perinatal overexpression of Zdhhc3 in cardiomyocytes." (PMID 37926281, 2023). "However, deletion of Rac1 in the heart did not alter the progression of Zdhhc3 overexpression–driven cardiomyopathy." (PMID 37926281, 2023).